FEN1 (flap structure-specific endonuclease 1)
Diseases named in the same sentence as FEN1 in open-access papers (continued):
Sharing a sentence is not in itself a finding about the gene and the disease.
cancer (continued). "In the current study, we further investigate the activity of N-hydroxyurea series inhibitors of FEN1 in human cancer cells by high-throughput and targeted means." (PMID 28628639, 2017). "As an important tumor suppressor, FEN1 expression is related to the development of cancer and the progression of the disease." (PMID 27801669, 2016). "It has been reported that FEN1 expression is related to the development and progression of various cancers." (PMID 27801669, 2016). "Conversely, overexpression of YY1 in the cancer cells suppresses FEN1 expression and sensitizes cancer cells to DNA damaging drugs." (PMID 25885449, 2015). "FEN1 plays an essential role in DNA replication; consequently, high levels of FEN1 are believed necessary to support hyperproliferation of cancer cells." (PMID 26431531, 2015). "Many cancers also show high levels of FEN1 expression, which in some cases is correlated with tumor aggression." (PMID 26431531, 2015). "One example illustrating the importance of the anti-cancer role of FEN1 was demonstrated using FEN1 knockout mice." (PMID 26668074, 2015). "Upon treatment with cancer drugs, YY1 is released from the FEN1 promoter so that the expression of FEN1 is highly induced in cancer cells, consequently leading to drug resistance." (PMID 25885449, 2015). "All pair-wise combinations between the three “central” synthetic lethal partner genes, WDHD1, FEN1, and CHTF8, and the ten outer cancer-mutated CIN genes were evaluated for synthetic lethality." (PMID 23382697, 2013). "A subsequent study expanded this initial proof-of-principle to include five additional genes, which are frequently mutated in cancer (CDC4, MRE11A, RNF20, SMC1A, and SMC3) that are also selectively killed following FEN1 inhibition." (PMID 24202319, 2013). "We have demonstrated the potential of this approach to identify targets and therapeutics, such as FEN1 and the flap endonuclease inhibitors described here, having potentially broad applicability in the treatment of cancer." (PMID 23382697, 2013). "Furthermore, XPF knockout or inhibition displays synergistic effects with FEN1 inhibitor in killing cancer cells." (PMID 41279254, 2025). "The results revealed that this combination not only effectively killed NB cells but also amplified the cytotoxic effects of cisplatin, positioning FEN1 as a promising anti-cancer target and underscoring the potential of its inhibitors to enhance treatment outcomes for NB." (PMID 40612863, 2025). "Additionally, small-molecule FEN1 inhibitors and small-interfering RNAs of FEN1 selectively killed human cell lines deficient in BRCA1 and BRCA2, confirming the sensitivity of these cancers to FEN1 deficiency." (PMID 40240755, 2025). "Knockdown of PRMT1, which destabilizes FEN1, can induce DNA damage and apoptosis of cancer cells." (PMID 40001488, 2025). "FEN1 was reported to promote cancer cell proliferation, migration, and invasion in biliary tumors." (PMID 38790250, 2024). "In addition, among the TCGA‐MM patients, high expressions of either FEN1, RBX1, and COX8A were significantly associated with poor overall survival and cancer‐specific survival." (PMID 39206872, 2024). "FEN1-IN-4 could also help control tumor progression in cancer therapy by slowing population growth, generating DSB and triggering senescence and cell death." (PMID 38396787, 2024). "Therefore, FEN1 or DNA2 inhibitors can induce synthetic lethality with BRCA1/2 deficiency and/or with PARPi in human cancer cells." (PMID 38714348, 2024). "FEN1 is a core protein in the base excision repair pathway and participates in Okazaki fragment maturation during DNA replication, which is an effective method for treating cancer as a monotherapy or in combination with other treatments." (PMID 38725628, 2024). "Targeting FEN1 has been verified as an effective strategy in mono or combined treatment of cancer." (PMID 35883563, 2022).
cancer (continued). "FEN1 has also been found to be closely related to tumor chemotherapy resistance, and is considered to be a marker of metastasis and poor prognosis of various malignant tumors." (PMID 35883563, 2022). "Small-molecule compounds targeting FEN1 have also been developed and detected in cancer regression." (PMID 35883563, 2022). "We look forward to new insights and applications on FEN1 inhibitors in cancer therapy." (PMID 35883563, 2022). "Therefore, developing small-molecule inhibitors targeting FEN1 is a good strategy for the treatment of cancers." (PMID 35883563, 2022). "In addition, FEN1 can modify the epigenetic features in cancer cells by inducing the upregulation of DNA methyltransferase 1 (DNMT1) and DNMT3a and interacting with DNMT3a through proliferating cell nuclear antigen (PCNA)." (PMID 36672839, 2022). "Interestingly, FEN1 is frequently overexpressed in cancers, and its upregulation accelerates tumorigenesis in a mouse model." (PMID 35414100, 2022). "The data presented so far provide evidence that FEN1 targeting is a promising anti-cancer approach." (PMID 33919707, 2021). "FEN1 overexpression has been commonly observed in cancer lines and human tumors." (PMID 33919707, 2021). "The oligonucleotides designed on the spherical nucleic acids can encode the substrate chain of FEN1 for fluorescence sensing, the aptamer sequence of AS1411 for cancer cell recognition and targeting, and the GC-rich sequence for loading the anticancer drug Dox." (PMID 34944499, 2021). "In fact, gene up-regulations are rampant in different cell phenotypes such as in cancer pathologies, an example being the up-regulation of flap endonuclease 1 (FEN1) in cancer progression and up-regulation of the small GTP-binding protein, RhoA, in vascular hypertension." (PMID 33971820, 2021). "Thus, the fabricated spherical nucleic acid can accurately target cancer cells and tumors and explicitly show FEN1 levels for early tumor diagnosis." (PMID 34944499, 2021). "FEN1 has an essential role in cancer evolution and progression." (PMID 34117958, 2021). "Alteration of FEN1 in cancer cells makes it a potential target for anticancer therapy." (PMID 34117958, 2021). "Hence, FEN1 overexpression and FEN1 promoter hypomethylation were suggested to be promising biomarkers in cancer." (PMID 34809722, 2021). "The flap endonuclease 1 (FEN1) gene is overexpressed in multiple malignant tumors and may promote tumor aggressiveness." (PMID 32399086, 2020). "Interestingly, Fen1 haploinsufficiency accelerated cancer progression in Apc mutant mice, leading to an increased number of intestinal adenocarcinomas, characterized by microsatellite instability (MSI)." (PMID 32547565, 2020). "Pan-cancer data downloaded from TCGA database were used to evaluate FEN1 mRNA expression levels." (PMID 32399086, 2020). "Similarly, analysis of protein expression in the pan-cancer TMA showed a high FEN1 expression in HCC compared to adjacent normal tissues." (PMID 32399086, 2020). "As FEN1 was involved in DNA repair and was overexpressed in the drug resistant cells, we hypothesized that manipulating FEN1 may alter the response of cancer cells to chemotherapeutic drugs that induce DNA damage." (PMID 32586310, 2020). "Furthermore, manipulating FEN1 altered the sensitivity of cancer cells to chemotherapeutic drug 5-Fu." (PMID 32586310, 2020). "In addition, FEN1 is a known biomarker for various cancers but its expression in HCC tissue is unclear." (PMID 31402791, 2019). "FEN1 expression correlates with cancer grade, aggressiveness and survival." (PMID 31402791, 2019). "In addition, highly sensitive and specific nanoprobes were designed to regulate FEN1 activity in human cancer cells and acted as anticancer drugs." (PMID 31402791, 2019). "Previous studies had confirmed that FEN1 was aberrantly up-regulated in various cancers." (PMID 31534853, 2019).
cancer (continued). "Researchers hypothesized that increased FEN1 mRNA expression in lung and gastrointestinal cancers in c.4150TT homozygotes could be due to unsuccessful binding of miRNA." (PMID 30260965, 2018). "Over-expression of FEN1 find in much type of cancer cells, over expression may involve tumor development it influence the cell proliferation and cell differentiation." (PMID 28187440, 2017). "FEN1 has been suggested to be required in fast‐dividing cells, such as cancer cells." (PMID 28371273, 2017). "This information suggested that FEN1 is a potential biomarker for certain cancer types." (PMID 28187440, 2017). "IC50 of HELF (48.7 μm) was much higher than that of A549 cells, indicating that the expression of FEN1 in different cancer cells could be correlated with their sensitivity to FEN1 inhibitor." (PMID 28371273, 2017). "FEN1 inhibitor could be used as a stand‐alone agent for blocking cancer cell proliferation or combining with DNA damage‐inducing agents to augment the therapeutic efficacy." (PMID 28371273, 2017). "Based on the results above, we inferred that a FEN1‐specific inhibitor might be able to serve as an anticancer drug which could be either used alone to suppress cancer cell growth or combined with DNA damage‐inducing agents to improve therapeutic efficacy." (PMID 28371273, 2017). "PPI networks used as a biomarker for diagnosis of cancer, FEN1 is over expressed in many cancer cells, previously identified PPI data act as a biomarker to confirm the FEN1 levels in diagnosis sample when compare to normal, this information supports to early detection of diseases." (PMID 28187440, 2017). "To support the notion that different DNA damage agents and therapeutic drugs induce FEN1 gene expression, we employed an expression array of 26 cancer cell lines in 13 major categories that have been treated with 25 different DNA-damaging agents and therapeutic drugs." (PMID 25885449, 2015). "However, it is unclear about the transcription factors that regulate FEN1 expression in human cancer." (PMID 25885449, 2015). "Consequently, cancer cells become more resistant to drugs due to enhanced DNA repair systems as a result of FEN1 over-expression." (PMID 25885449, 2015). "More importantly, it is unknown whether up-regulation of FEN1 has an adverse impact on the prognosis of chemotherapeutic treatments of human cancers." (PMID 25885449, 2015). "In support of this hypothesis, deficiency in FEN1 causes partially similar phenotypes as FANCA, i.e. inflammation and cancers." (PMID 24349332, 2013). "Our own bioinformatics analyses and sequencing data corroborate these findings, demonstrating that FEN1 expression is markedly elevated in stage IV NB compared to earlier stages, suggesting its potential as a prognostic indicator for adverse outcomes in this cancer." (PMID 40612863, 2025). "Even though our and others’ previous studies show that FEN1 deficiency/inhibition and PARP1 inhibition synergistically kill cancer cells, our new observations suggest that the efficacy of combined FEN1 inhibition and PARP1 inhibition in killing cancer cells may at least partly depend on LIG1 status." (PMID 41280084, 2025). "Furthermore, XPF and FEN1 inhibitors show synergistic effects in killing human cancer cells." (PMID 41279254, 2025). "In addition, by inducing a G2/M arrest, FEN1-IN-4 could be a useful adjunct to radiotherapy to bring cancer cells into a radiosensitive phase, thereby improving the efficacy of radiotherapy." (PMID 38396787, 2024). "Moreover, overexpression of FEN1 contributes to drug resistance in several types of cancers." (PMID 35883563, 2022). "All this supports the hypothesis that FEN1 could be a therapeutic target for cancer treatment." (PMID 35883563, 2022). "Consequently, this increased FEN1 level may have a role in the resistance to other DNA damage agents which eventually leads to an increased rate of cancer cell proliferation." (PMID 34117958, 2021).
cancer (continued). "Furthermore, FEN1 overexpression might be one of the main reasons for genome instability and impaired DNA replication in cancer cells." (PMID 34117958, 2021). "Therefore, research frontier directions of FEN1 can be predicted as follows: mechanism research related to oxidative stress; research related to phosphorylation; mechanisms in occurrence, progression and therapy resistance in cancer." (PMID 33827468, 2021). "In established tumors, on the other hand, FEN1 may promote cancer progression and survival." (PMID 33919707, 2021). "Existing studies have shown that FEN1 is highly expressed in various cancers, such as brain (Nikolova, Christmann & Kaina, 2009), lung, breast, gastric (Wang, Xie & Chen, 2014), prostate and pancreatic cancer, but its expression and role in HCC remains unclear." (PMID 31534853, 2019). "We hypothesized that the inhibition of FEN1 could suppress cancer growth by blocking DNA synthesis." (PMID 28371273, 2017). "In addition to its role in DNA replication, increased FEN1 expression may also be a response to severe DNA damage in cancer cells." (PMID 28371273, 2017). "Mutated FEN1 (FFAA FEN1) and PCNA complex may cause FEN1 deficiency, which influence on Base Excision repair and RNA primer removal, leading to numerous DNA breaks this develops aneuploidy- associated cancer." (PMID 28187440, 2017). "Thus, inhibition of FEN1 in some cancers may be a potential target for their treatment." (PMID 39759116, 2025). "Among the interface genes in the Her2+_TNBC module, the known cancer-related genes are mostly DNA repair genes, such as BARD1, BRIP1, BRCA1, BRCA2, FANCA, FANCC, FANCD2, and FEN1." (PMID 35992864, 2022). "Flap endonuclease 1 (FEN1) exhibits multiple values in the early diagnosis, targeting therapy, and prognostic monitoring of various cancers." (PMID 35884331, 2022). "Evidence suggests that NF-κB/p65 directly binds to the FEN1 promoter and enhances FEN1 transcription, which contributes to the AKT signaling pathway to drug resistance in cancer cells." (PMID 35246224, 2022). "Furthermore, reduced activity of BER system involving MTH1, OGG1 and FEN1 in hypoxic conditions could lead to increased formation of observed oxidative DNA damage due to decreased repair capacity and thereby could render cancer cells less dependent to MTH1." (PMID 34831264, 2021). "Currently, specific inhibitors against BER proteins such as Polβ, PNKP, FEN1, Ligase IIIα, and PARP1/PARG have been developed either to sensitize several cancers or to form synthetic lethal partnerships with common cancer mutations." (PMID 33553154, 2020). "In summary, we show that FEN1 is up-regulated in HCC tissue and human hepatoma cell lines compared to para-cancer normal liver tissues and normal hepatocyte cell lines." (PMID 31402791, 2019). "There are many reports about the relationship between cancer and endonucleases including apurinic/apyrimidinic endonuclease 1 (APE1), Flap endonuclease-1 (FEN1) and Dicer." (PMID 30064372, 2018). "Therefore, targeting FEN1 could serve as a potent strategy for cancer therapy." (PMID 28187440, 2017). "FEN1 has been identified as a pro-tumor gene that promotes tumor progression in various cancer types; however, its role in NB had not been previously studied." (PMID 40612863, 2025). "Our studies aiming to expand the potential clinical reach of FEN1 inhibitors beyond the HRD setting, identified EWS cells and more generally, SLFN11 expressing cancer cells, as potentially sensitive populations, which is consistent with the role of Schlafen-11 in response to RS-inducing DDRi/DDAs." (PMID 41359388, 2025).
cancer (continued). "The endonuclease FEN1 resects the generated flap before final nick ligation by DNA ligase I. The reconstitution of long-patch-BER has demonstrated an absolute requirement for the endonuclease activity of FEN1, which, is often upregulated in cancers." (PMID 32850380, 2020). "In our study, m6A-seq and RNA-seq revealed that FEN1 was the downstream gene of IGF2BP2 and confirmed the oncogenic effect of FEN1 and revealed an m6A-dependent regulatory mechanism to partially explain the common upregulation of FEN1 in cancer." (PMID 33224879, 2020). "Polyploidy in cancer cells could lead to the overexpression of BRCA1, p19arf and other DNA repair genes in FEN1 mutant cells." (PMID 26668074, 2015). "Flap endonuclease 1 (FEN1) plays critical roles in DNA replication and repair and in counteracting replication stress, which is a key mechanism for many chemotherapeutic drugs to kill cancer cells." (PMID 25885449, 2015). "The expression of breast cancer 1, early onset (BRCA1), RAD51, bloom syndrome, RecQ helicase-like (BLM), flap-endonuclease 1 (FEN1), uracil-DNA glycosylase (UNG), damage-specific DNA binding protein 2 (DDB2) and exonuclease 1 (EXO1) were significantly suppressed after 24 h ZEA treatment." (PMID 24788721, 2014). "This suggests that endogenous replication stress or spontaneous DNA damage in human cancer cells activates DDR checkpoints, promoting the formation of 3’ flaps and subsequent recruitment of XPF to replication forks for 3’ flap processing, even in the presence of proficient FEN1 function." (PMID 41279254, 2025). "Finally the human RAD27 homolog FEN1 and RAD52, as well as many other genes involved in DNA replication, repair and recombination, can be over- or under-expressed in human cancers thus producing genetic instability." (PMID 31164905, 2019). "However, TYMS, DUT, POLB, LIG1 and FEN1 have been identified by others as PARGi synthetic lethality genes, and these observations support the notion that inhibition of nucleotide biosynthesis and BER can sensitize cancer cells to pharmacological PARG inhibition." (PMID 39015544, 2024). "Some of the interactions like APC and FEN1 may promote the cancer, adenomatous polyposis coli (APC) and Flap Endonuclease both are tumor oppressors but when APC interact with FEN1, this interaction inactivate the tumor suppressor activity and promote the cancer through novel mechanisms." (PMID 28187440, 2017). "High-throughput screens of human cancer cell-lines identify colorectal and gastric cell-lines with microsatellite instability (MSI) as enriched for cellular sensitivity to N-hydroxyurea series inhibitors of FEN1, but not the PARP inhibitor olaparib or other inhibitors of the DNA damage response." (PMID 28628639, 2017).